EPHX2 (epoxide hydrolase 2)
Diseases named in the same sentence as EPHX2 in open-access papers (continued):
Sharing a sentence is not in itself a finding about the gene and the disease.
chronic kidney disease (13 papers, 2010 to 2025). Impairment of the renal function secondary to chronic kidney damage persisting for three or more months. "We aimed to assess the possible association between two functional polymorphisms of the EPHX2 gene (rs2741335 and rs11780592) with oxidized LDL (ox-LDL), carotid atherosclerosis, mortality, and cardiovascular (CV) disease in 118 patients with diabetic chronic kidney disease (CKD)." (PMID 34040693, 2021).
acute kidney injury (12 papers, 2010 to 2024). Sudden and sustained deterioration of the kidney function characterized by decreased glomerular filtration rate, increased serum creatinine or oliguria. "We genotyped patients in two independent cardiac surgery cohorts for functional EPHX2 polymorphisms, Lys55Arg and Arg287Gln, and determined AKI using Acute Kidney Injury Network criteria." (PMID 28552948, 2017). "Experimental inhibition of soluble epoxide hydrolase had blood pressure lowering effects in renovascular hypertension and a gain-of-function EPHX2 polymorphism was shown to be associated with an increased incidence of acute kidney injury following cardiac surgery." (PMID 31083566, 2019). "We hypothesized that sEH gene (EPHX2) deletion would increase endogenous EET levels and thereby protect against I/R-induced acute kidney injury (AKI)." (PMID 26727266, 2016).
Cerebral ischemia (12 papers, 2013 to 2025). Restriction of arterial blood supply to the brain associated with insufficient oxygenation to support the metabolic requirements of the tissue. "Another study has shown that EPHX2 gene knockout can increase cerebral blood flow, reduce infarct volume in rats with middle-arterial artery occlusion, and has a protective effect on cerebral ischemia." (PMID 36846137, 2023). "Three of them (Ephx2, F2r and Il18) are known as contributing to brain ischemia." (PMID 32039698, 2019).
prostate carcinoma (12 papers, 2017 to 2025). A carcinoma that arises from epithelial cells of the prostate gland. "Recent studies have suggested that EPHX2 deregulation is significantly associated with prostate cancer progression and poor prognosis." (PMID 40129060, 2025). "The downregulation of EPHX2 expression is associated with poor prognosis and clinical characteristics of liver cancer and prostate cancer." (PMID 35433439, 2022). "Dysregulation of Ephx2 can contribute to carcinogenesis and more aggressive clinical phenotypes in the prostate, liver, and kidney (76, –78) and is highly expressed in prostate cancer." (PMID 38330013, 2024). "EPHX2 is expressed in various human malignant neoplasms, including prostate cancer, hepatocellular carcinoma, and colon cancer." (PMID 39125591, 2024). "In prostate cancer and hepatocellular carcinoma, EPHX2 was downregulated, which was significantly correlated with the progression of tumors." (PMID 36176391, 2022). "However, another study inhibiting EPHX2 reduced the viability of prostate cancer cells in combination with other treatments such as androgen deprivation or induction of oxidative stress." (PMID 39125591, 2024). "In addition, silencing of EPHX2 has been proved to reduce tumor cell viability, induce apoptosis, and inhibit androgen receptor signaling in prostate cancer." (PMID 35236335, 2022). "The silence of EPHX2 could induce apoptosis in prostate cancer cells by reducing androgen receptor signalling." (PMID 33020551, 2020). "In prostate cancer, the genes PLA2G7, HPGD, EPHX2, and CYP4F8 exhibit significantly altered expression." (PMID 38172792, 2024). "Previous studies confirmed that EPHX2, RXRA, LTC4S and SLC25A17 were abnormally expressed in prostate cancer tissues and affected the malignant biological behaviour of prostate cancer cells and prognosis of patients." (PMID 36643625, 2023). "We found one amplified gene in the in-frame fusion samples, hydroxyprostaglandin dehydrogenase 15-(NAD) (HPGD), which was reported as a therapeutic target in prostate cancer due to its involvement in the arachidonic acid pathway with PLA2G7, EPHX2, and CYP4F8." (PMID 29299133, 2017).
breast cancer (10 papers, 2014 to 2024). A primary or metastatic malignant neoplasm involving the breast. "Therefore, it can be speculated that the high expression of exons corresponding to HerC4 and Ephx2 may be a risk factor for poor prognosis of breast cancer, and may be a more sensitive indicator than the parent gene." (PMID 33020551, 2020). "In conclusion, this study found that DDX39B, EPHX2 (exo7), and HERC4 (exo23) can be used as potential targets for the treatment of breast cancer, which provides a new idea for the treatment of breast cancer." (PMID 33020551, 2020). "In addition, this agrees with our present study, where EPHX2 overexpression significantly correlated with TNBC, a heterogeneous and aggressive form of breast cancer, lacking therapeutic targets and with poor prognosis." (PMID 39125591, 2024).
Hypercholesterolemia (10 papers, 2014 to 2025). An increased concentration of cholesterol in the blood. "Mutations of EPHX2 are associated with familial hypercholesterolemia, and EPHX2 has also been proven to exacerbate acute vascular inflammatory responses, suggesting its role in lipid metabolism and inflammation." (PMID 37180171, 2023). "Case 5 (19ZC161) has four missense variants, including rs751141, in the hydrolase EPHX2 gene, associated with hypercholesterolemia (OMIM#143890), and rs761270780, in the CTDP1 gene." (PMID 33815474, 2021). "Because EPHX2 has been linked to lipid traits and hypercholesterolemia is common in AN patients, the authors performed a variety of interaction tests between variants in EPHX2 and cholesterol and body mass index." (PMID 24705293, 2014).
liver fibrosis (9 papers, 2018 to 2024). "The use of an additional sEHI (t-TUCB) as well as Ephx2−/− mice validated these results, suggesting a pathological role for sEH in liver fibrosis." (PMID 32545637, 2020). "In addition, up-regulation of genes involved in tissue injury and hepatic fibrosis (Adora1), caspase-dependent apoptosis (Moap1), and oxidative stress and antioxidant defense (Ephx2 and Oxr1) was identified only in the liver treated with Zn ions." (PMID 33567653, 2021).
Sepsis (9 papers, 2020 to 2025). Sepsis is defined as life-threatening organ dysfunction caused by a dysregulated host response to infection. "In the present study, we identified 5 lipid metabolism-related hub genes (MAPK14, EPHX2, BMX, FCER1A, and PAFAH2) that have the possibility of diagnostic and therapeutic in patients with sepsis by machine learning analysis." (PMID 37180171, 2023). "However, the relative expression levels of BEX1, and EPHX2 were significantly higher in the sepsis group than those in the control group." (PMID 40526611, 2025). "Therefore, EPHX2 is a good candidate for predicting the prognosis of sepsis." (PMID 37180171, 2023).
colitis (8 papers, 2013 to 2024). Inflammation of the colon. "Consistent with the increased expression of Ephx2 in the HFDs, we recently showed that a diet high in SO leads to increased levels of oxylipins in the intestines and correlates with barrier dysfunction and susceptibility to colitis in mice." (PMID 38151490, 2023). "Ephx2 converts linoleic and arachidonic acid epoxides into bioactive oxylipins; we recently showed that a diet high in SO leads to increased levels of these oxylipins in the intestines and correlates with barrier dysfunction and susceptibility to colitis in mice." (PMID 37886485, 2023). "In mice, either genetic deficiency of EPHX2 or treatment with a tool EPHX2i have been reported to attenuate chronic active IBD in IL10 (-/-) and in DSS-induced colitis models." (PMID 31002701, 2019). "EPHX2 tool inhibitors have been reported to inhibit colitis and ulcer formation in dextran sodium sulfate (DSS)-induced, and in IL10 (interleukin 10) knockout mouse IBD models." (PMID 31002701, 2019). "The fact that EPHX2 inhibition appears beneficial in both the DSS and IL10 knockout (KO) colitis models is particularly interesting, since they are driven by very different mechanisms." (PMID 31002701, 2019).
colorectal cancer (7 papers, 2019 to 2025). A primary or metastatic malignant neoplasm that affects the colon or rectum. "Expressions of EPHX1 and EPHX2 were significantly decreased in CRC and presented as diagnostic and prognostic biomarkers for colorectal cancer." (PMID 41465541, 2025). "Studies have found that the EPHX2 gene can inhibit the development of colorectal cancer by inhibiting lipid metabolism." (PMID 39769164, 2024). "For example, EPHX2 was identified as a tumor suppressor in colorectal carcinoma (CRC), which repressed CRC progression by inducing fatty acid degradation." (PMID 36568396, 2022).
myocardial ischemia (7 papers, 2016 to 2025). A disorder of cardiac function caused by insufficient blood flow to the muscle tissue of the heart. "Genetic disruption of EPHX2 results in increased epoxide:diol ratios and improves functional recovery following cardiac ischemia/reperfusion injury." (PMID 28384353, 2017).
cardiac arrest (6 papers, 2016 to 2025). Cessation of breathing and/or cardiac function. "Previous studies have shown that the deletion of the EPHX2 gene decreases the survival rate after cardiac arrest." (PMID 40129060, 2025).
Hepatic steatosis (6 papers, 2012 to 2024). Steatosis is a term used to denote lipid accumulation within hepatocytes. "In order to evaluate the functional contribution of the CYP epoxygenase pathway to the regulation of fatty liver disease-associated hepatic inflammation and injury, we administered the atherogenic diet to Ephx2−/− mice." (PMID 25310404, 2014).
hepatocellular carcinoma (6 papers, 2014 to 2025). A malignant tumor that arises from hepatocytes. "In some tumor types, such as hepatocellular carcinoma and colon cancer, low EPHX2 expression has been associated with good prognosis." (PMID 39125591, 2024). "Compared with the normal human hepatocyte cell line L‐O2, EPHX2 was highly expressed in the human hepatoma cell lines, HUH‐7 and HepG2." (PMID 40129060, 2025). "Here, we identified a critical tumor-promoting and prometastatic role for chemotherapy-generated pancreatic and hepatocellular cancer cell debris, which triggers a storm of proinflammatory eicosanoid-driven cytokines via the upregulation of Ephx2 and Ptger4." (PMID 34607951, 2021).
pulmonary hypertension (6 papers, 2010 to 2024). Increased pressure within the pulmonary circulation due to lung or heart disorder. "To date, there is little attention paid to the intrinsic causation between the estrogen-driven physiological downregulation of Ephx2 gene/sEH and female-susceptibility to be pulmonary hypertensive, a topic that is being investigated in our laboratories." (PMID 30420806, 2018).
colon carcinoma (5 papers, 2022 to 2025). "Additionally, the expression of EPHX2 in the human colon carcinoma cell lines, HT29 and HCT8, was significantly increased compared with the human intestinal epithelial cell line (HIEC)." (PMID 40129060, 2025). "EPHX2 could inhibit colon cancer progression by promoting fatty acid degradation." (PMID 36531021, 2022). "CPTAC proteomic data also revealed lower total protein expression of EPHX2 in BRCA, ovarian cancer, colon cancer, ccRCC, UCEC, and LUAD." (PMID 40129060, 2025). "The clinical correlation between EPHX2 and CRC was explored, the inhibitory effect of EPHX2 on the progression of CRC was confirmed, and a real lipid metabolism model of colon cancer with the participation of EPHX2 was preliminarily established." (PMID 35433439, 2022). "Because it is not disturbed by the anoxic microenvironment of colon cancer, it cannot evaluate whether the hypoxic microenvironment of CRC is related to the expression of EPHX2." (PMID 35433439, 2022).
essential hypertension (5 papers, 2014 to 2025). Hypertension that presents without an identifiable cause. "Taken together, we provide genetic evidence that the mutation of R287Q variant in EPHX2 gene was associated with low enzyme activity of soluble epoxide hydrolase and reduced risk of having primary hypertension." (PMID 32181010, 2020). "Zhu and colleagues examined the association of EPHX2 gene R287Q variant with the risk for primary hypertension in three ethnic groups (Uygur, Kazakh, and Han) from Xinjiang, and this variant was identified as an independent protective factor in Han Chinese only." (PMID 32181010, 2020). "Based on above evidence, it is hence tempting to speculate that EPHX2 gene R287Q variant, if involved, might contribute to the development of primary hypertension via affecting the enzyme activity of soluble epoxide hydrolase." (PMID 32181010, 2020). "To test this hypothesis, we aimed to assess the association of a missense mutation at exon 8, R287Q (rs751141), in EPHX2 gene with the risk of primary hypertension in Han Chinese and examine the association of this variant with enzyme activity of soluble epoxide hydrolase." (PMID 32181010, 2020). "Recent findings suggest that EPHX2 may play a role in primary hypertension in humans." (PMID 40009070, 2025).
inflammatory bowel disease (5 papers, 2015 to 2023). A spectrum of small and large bowel inflammatory diseases of unknown etiology. "Secondly, functional epoxide hydrolase 2 (EPHX2), which promotes macrophage infiltration and maturation, and its inhibition is considered a pharmaceutical strategy against inflammatory bowel disease." (PMID 37443766, 2023). "Using a Connectivity Map (CMAP) approach, we identified an inverse-correlation between an exemplar EPHX2 inhibitor (EPHX2i) compound response and an inflammatory bowel disease patient-derived signature." (PMID 31002701, 2019).
lung disease (5 papers, 2017 to 2024). "In this way, Ephx2 deficiency may protect individuals from CS-induced lung disease." (PMID 28028752, 2017).
melanoma (5 papers, 2022 to 2025). A malignant, usually aggressive tumor composed of atypical, neoplastic melanocytes. "EPHX2 inhibitors can promote the progression of melanoma and fibrosarcoma in mouse models by increasing the level of endogenous lipid mediators, which indicates that there is a relationship between EPHX2-lipid metabolisms." (PMID 36613632, 2022). "Moreover, studies have indicated that inhibitors of EPHX2 can accelerate the progression of melanoma and fibrosarcoma in murine models by augmenting levels of the endogenous lipid mediator epoxyeicosatrienoic acid (EET), further implicating EPHX2 in lipid metabolism and tumor progression." (PMID 40538850, 2025). "According to Panigrahy, EPHX2 inhibitors can promote the progression of melanoma and fibrosarcoma in mouse models by increasing the level of an endogenous lipid mediator, epoxy eicosatrienoic acid (EETs), suggesting that a relationship exists between EPHX2-lipid metabolism and tumor progression." (PMID 35433439, 2022). "Taken together, ALDH2, ADH1B, ALDH3A2, DPT, EPHX2, and GATM are potential biomarkers of melanoma, which have high prediction values for melanoma." (PMID 38378847, 2024). "After literature research, we chose 6 hub genes: ALDH2, ADH1B, ALDH3A2, DPT, EPHX2, and GATM, which were rarely reported in melanoma as the object of this research to explore their accuracy in the diagnosis and prediction of melanoma." (PMID 38378847, 2024).
Anxiety (4 papers, 2017 to 2026). Intense feelings of nervousness, tension, or panic often arise in response to interpersonal stresses. "This is different finding compared with a study done in Japan where the carrier of AA genotype in SNP (rs17466684) of EPHX2 was found to be a risk variant of anxiety particularly panic disorder." (PMID 31801286, 2019).
coronary artery calcification (4 papers, 2017 to 2020). Calcification of the coronary artery, used as a measure of coronary atherosclerosis, a risk factor for myocardial infarction. "Exonic polymorphisms in EPHX2 are associated with coronary artery calcification." (PMID 29227965, 2017).
schizophrenia (4 papers, 2019 to 2022). A major psychotic disorder characterized by abnormalities in the perception or expression of reality. "The expression of EPHX2 mRNA in induced pluripotent stem cell-derived neurospheres was higher among schizophrenia patients than the controls." (PMID 35563342, 2022). "Expression of EPHX2 mRNA from schizophrenia and ASD have been found higher than that of controls." (PMID 36176292, 2022).
steatosis (4 papers, 2012 to 2023). Increased lipid within the cytoplasm of cells. "The study found that Ephx2 was significantly increased in the liver of mice after ingesting ethanol, and in Ephx2 knockout mice, Ephx2 deficiency ameliorated ethanol-induced liver damage, inflammation, and steatosis." (PMID 37795374, 2023).
breast tumors (3 papers, 2020 to 2024). "In conclusion, our work is the first study describing the nuclear expression of EPHX2 in breast tumors (BC)." (PMID 39125591, 2024).
lung carcinoma (3 papers, 2023 to 2025). "Studies have shown that certain polymorphisms in the promoter region of the EPHX2 gene may affect the metabolism of lung cancer-related substances by regulating the activity of related enzymes, thereby participating in the occurrence and development of lung cancer." (PMID 40538850, 2025). "Knockdown of 16 of 18 (89%) CPD genes reduced viability in both cell lines —including five targets not previously implicated in lung cancer (Ephx2, Peg3, Apob, Oit1 and Slc6a19)." (PMID 40825871, 2025). "Although few samples had mutations in PBK, we observed that mutations in CNV accounted for the majority of PBK gene DNA alterations in all lung cancer patients and found a high proportion of LUAD patients with CNV with multiple tumor suppressor genes, such as CCDC25, SCARA5 and EPHX2." (PMID 37993518, 2023).
lupus (3 papers, 2019 to 2024). "We assessed the influence of EpFAs and their metabolites in lupus prone NZB/W F1 mice by pharmacological inhibition of soluble epoxide hydrolase (sEH, EPHX2)." (PMID 31222024, 2019).
Myocardial fibrosis (3 papers, 2014 to 2018). "Histochemical staining revealed that compared with pharmacological inhibition, EPHX2 deletion aggravated AngII-induced myocardial fibrosis; the mRNA levels of fibrotic-related genes were increased." (PMID 24718617, 2014).
pancreatitis (3 papers, 2014 to 2024). Inflammation of the pancreas. "To determine the role of sEH during AP, we assessed the severity of cerulein-induced pancreatitis in control and Ephx2 KO mice as described in Methods." (PMID 25402489, 2014).
preeclampsia (3 papers, 2020 to 2024). Preeclampsia is a hypertensive disorder of pregnancy that is characterized by new-onset hypertension with proteinuria presenting after 20 weeks of gestation, and depending on mild or severe forms may initially present with severe headache, visual disturbances, and hyperreflexia. "Here, we sequenced the promoter region of EPHX2 to investigate the association between promoter sequence alterations that we thought to affect the expression levels of the enzyme and preeclampsia (PE)." (PMID 33312058, 2020).
septic shock (3 papers, 2012 to 2024). Shock caused by infection; frequently caused by gram negative bacteria, although some cases have been caused by other bacteria, viruses, fungi, and protozoa; characterized by fever, chills, tachycardia, tachypnea, and hypotension. "In this study, we recognized four immune-mitochondrial key genes (PGS1, C6orf136, THEM4, and EPHX2) in septic shock and designed a novel gene diagnosis model that provided a new and meaningful way for the diagnosis of septic shock." (PMID 39609718, 2024).
tauopathy (3 papers, 2019 to 2025). Neurodegenerative disorders involving deposition of abnormal tau protein isoforms (tau proteins) in neurons and glial cells in the brain. "Here we investigated the mechanisms and functional role of the sEH-EET axis in tauopathy by treating PS19 mice with a small molecule sEH inhibitor TPPU and by crossing the PS19 mice with Ephx2 (gene encoding sEH) knockout mice." (PMID 40264187, 2025).